CCK (cholecystokinin)
Diseases named in the same sentence as CCK in open-access papers (continued):
Sharing a sentence is not in itself a finding about the gene and the disease.
Obesity (continued). "A trypsin inhibitor isolated from tamarind seed (TTI) has satietogenic effects in animals, increasing the cholecystokinin (CCK) in eutrophy and reducing leptin in obesity." (PMID 29322840, 2018). "A reduced sensitivity to a satietogenic dose of CCK, leading to hyperphagia, has already been shown in obesity-prone rats receiving standard chow as well as in high-fat diet fed rats." (PMID 28443064, 2017). "The role of alteration of CCK secretion in obesity is uncertain: indeed, obese patients exhibit higher CCK plasmatic levels that lean individuals, either in fasting conditions or after a high-fat meal." (PMID 28966594, 2017). "These peptides are thus suggested as a promising functional food against obesity via regulation of cholecystokinin release." (PMID 26132844, 2015). "The production of some of these gastric derived signals has been proved to be altered in obesity (ghrelin, CCK, and GLP-1)." (PMID 25960740, 2015). "Global deletion of PrRP (in a loxSTOPlox-PrRP mouse) results in obesity and attenuated responses to leptin and CCK." (PMID 25176149, 2014). "A recent study proposes a potential role of the gut hormone cholecystokinin (CCK) for the pharmacotherapy of obesity." (PMID 25352831, 2014). "These animals exhibit approximately 25% higher food intake and moderate life-long obesity; moreover the hyperphagia in these animals is at least partly a consequence of insensitivity to CCK." (PMID 23816469, 2013). "The PAI-1-H/Kβ mice exhibit moderate hyperphagia and obesity probably because of resistance to the satiating actions of cholecystokinin (CCK) by suppression of vagal afferent stimulation." (PMID 23494120, 2013). "Finally, obesity perturbs CCK-dependent peri-islet exocrine cell transcriptional states and enhances islet-proximal tumor formation." (PMID 41760660, 2026). "Single-cell RNA-sequencing, in silico latent-space archetypal and trajectory analysis, and experimental lineage tracing in vivo reveal that obesity induces the expansion of postnatal immature β cells, which adapt to express CCK via stress-responsive JNK/cJun signaling." (PMID 41760660, 2026). "Therefore, CCK levels and their dysregulation in obesity require further study to establish a clear difference." (PMID 39997735, 2025). "Although CCK contributes to satiety and may support pancreatic function, its effects are blunted in obesity due to reduced vagal sensitivity and lower neuronal excitability." (PMID 41150735, 2025). "These might have value if CCK antagonists are used in malignancies, obesity, or with immunosuppressive therapies." (PMID 40586867, 2025). "Nevertheless, it has been shown that there is a resistance to CCK that develops in obesity." (PMID 39997735, 2025). "The contribution of PYY and CCK to obesity remains unclear as some studies report inconsistent hormone levels pre- and post-meal in individuals with obesity." (PMID 41441026, 2025). "Consequently, there has been an impressive interest in measuring intestinal CCK secretion in human obesity before as well as after various treatments (diets, exercise, gastric bypass, and sleeve surgery)." (PMID 40557463, 2025). "Correspondingly, it is ablation of ARC POMC, not NTS POMC neurons, which is required for the development of obesity, increased fat mass and glucose intolerance, with the former neurons being stimulated by leptin, while the latter are stimulated by cholecystokinin (CCK) and inhibited by opioids." (PMID 38019584, 2024). "Consequently, heightened lung CCK levels in the context of obesity are likely to impact lung function and exacerbate AHR." (PMID 38762465, 2024). "Components like milk fat, probiotics, and calcium in dairy products have anti-inflammatory effects, can increase fat oxidation, and promote the feeling of satiety through cholecystokinin and glucagon-like peptide-1, thus acting as preventive measures against obesity." (PMID 39582245, 2024). "Elevating the CCK levels is considered an effective strategy in combating obesity." (PMID 38731751, 2024).
Obesity (continued). "In the stress-induced obesity network, CCK inhibits NPY, which regulates the feeding behavior." (PMID 39062927, 2024). "Ongoing research and innovative approaches, including ghrelin receptor modulators, stable PYY analogues, positive allosteric modulators for CCK, and advanced amylin analogues or DACRAs, showcase the potential for more effective and targeted anti‐obesity medications." (PMID 39016695, 2024). "Notably, in an HFD-induced obesity model, one study revealed an autocrine stimulatory loop involving CCK-activated, CCKA receptor-mediated airway smooth muscle contraction, a process potentially exacerbated by elevated FFAs." (PMID 38762465, 2024). "This suggests that inhibiting the FFAs-CCK pathway via lipid-lowering agents could represent a promising strategy for treating individuals with asthma and obesity." (PMID 38762465, 2024). "Our data suggest that, at least in the mouse with obesity-associated AHR, the heightened CCK/CCKAR signaling in the lung appears to lead to increased ASM contraction that is independent of airway inflammation as CCKAR antagonists did not alter markers of inflammation." (PMID 36599824, 2023). "Dysfunctions in CCK or its effects on gastrointestinal function and appetite could potentially contribute to the initiation and persistence of obesity." (PMID 37891223, 2023). "Our data showing elevated CCK in the lungs of obese mice suggest that a heightened CCK/CCKAR signaling and subsequent ASM contraction may contribute to the development of obesity-associated AHR." (PMID 36599824, 2023). "In vivo, CCK is upregulated in the airways of diet-induced and genetically obese mice, suggesting that the hormone contributes to the heightened AHR associated with obesity." (PMID 36599824, 2023). "Moreover, CCK was negatively correlated with all obesity markers, which was annulled after controlling for BMI." (PMID 35334929, 2022). "Leptin, GLP-2, and CCK correlations with obesity markers were annulled when adjusting for BMI." (PMID 35334929, 2022). "Whether obesity affects CCK secretion is controversial and could be due to methodological problems in measuring CCK." (PMID 35334929, 2022). "However, the limited data in this area cannot be generalized to include the effect of exercise and physical activity on cholecystokinin levels in individuals with obesity." (PMID 35264977, 2022). "Studies have shown that reduced levels of cholecystokinin may contribute to a reduced feeling of fullness and make it more difficult for some individuals with obesity to lose weight." (PMID 35264977, 2022). "Indeed, our study provides the novel finding that density of GLP-1-positive cells is reduced in jejunum in T2D individuals with severe obesity whereas CCK-, GIP- and PYY- producing cell densities remained unaffected." (PMID 33037328, 2021). "Moreover, LPS leads to attenuated CCK-induced satiation and dysregulation of anorexigenic and orexigenic hormones expressed in vagal afferent neurons, concomitant with hyperphagia and obesity development." (PMID 33669189, 2021). "It is reported that plasma CCK levels were markedly lower in high-fat-fed prone (OP) rats than that of obesity-resistant rats after lipid gavage, implying that the decreased or deficit levels of CCK in OP rats might prone to weight gain and obesity." (PMID 33868169, 2021). "However, at least a subset of the studies with CCK-8 also demonstrated shortened interval between meals, offsetting the reduced caloric intake at a single meal; this has reduced the enthusiasm for CCK agonists as satiety agents for the treatment of obesity." (PMID 34149622, 2021). "It remains controversial whether obesity affects CCK secretion; both a reduction, an increase and unaltered postprandial CCK levels have been reported in obese subjects." (PMID 34072172, 2021).
Obesity (continued). "Cholecystokinin (CCK) is a gastrointestinal hormone that could potentially be used as an anti-obesity drug, as evidenced by the lowering of food intake observed after administration to rodents, pigs, monkeys and both lean and obese humans." (PMID 31175319, 2020). "Since insulin resistance and hyperglycemia are common correlates of obesity, we hypothesized that glucose may be regulating CCK expression in the islet." (PMID 32071395, 2020). "Diet-induced obesity attenuates AgRP neural and behavioral responses to CCK and ghrelin." (PMID 32720646, 2020). "Studies employing intraduodenal infusion of nutrients at different rates that mimic the physiological range of gastric emptying have shown that the secretion of GIP and CCK increases in an approximately linear pattern with increasing rates of infusion in health, obesity and T2DM." (PMID 32825608, 2020). "Interestingly, previous studies demonstrated that during stress states such as obesity, islets produce and secret cholecystokinin (CCK), this was shown to have a positive effect on beta cell mass." (PMID 31430329, 2019). "In this context, trypsin inhibitors, molecules with wide heterologous application, appear as possibilities in the treatment of overweight and obesity due to the action on satiety related mechanisms, mainly in the modulation of satiety hormones, such as cholecystokinin." (PMID 30734596, 2019). "It is controversial if obesity impacts CCK secretion [see for review,]." (PMID 31281260, 2019). "Thus, in the present study we purified, characterised, and partially sequenced the trypsin inhibitor of the tamarind seed, reevaluating its effect upon plasmatic CCK and leptin in an experimental model of obesity." (PMID 29322840, 2018). "For example, cholecystokinin (CCK) decreases energy intake, and gastric emptying is a major determinant of the initial (~15–30 min) glycemic response to carbohydrate–containing meals in health, obesity and type 2 diabetes." (PMID 29642492, 2018). "Studies related to gut and adipose tissue hormones and obesity suggest that obesity is associated with a blunted postprandial response of satiety factors such as GLP-1 and PYY, CCK and reduced postprandial suppression of orexigenic ghrelin, and some type of central leptin resistance." (PMID 26499438, 2016). "Marine peptides may be employed as anorexigenic agents and may interact with appetite-suppressing gut hormones including cholecystokinin and glucagon-like peptide 1 to produce anti-obesity effects." (PMID 26132844, 2015). "Our finding suggests a CCK dysregulation that might lead to reduced satiety signaling, boosting the development of obesity." (PMID 25010715, 2014). "In obesity, there is evidence for attenuation of the action of CCK in inhibiting gastric emptying." (PMID 23816469, 2013). "Since there is increased plasma PAI-1 in obesity it seems possible that this may also account for depression of responses to CCK." (PMID 23816469, 2013). "This suggests that reduced sensitivity to CCK results in hyperphagia and could directly lead to the development of obesity." (PMID 22412960, 2012). "We conclude that, in males with obesity, intraduodenal calcium, when administered alone, stimulates GLP-1 and PYY secretion and pyloric pressures and enhances the effects of Trp to stimulate CCK, GLP-1, and PYY secretion, associated with greater suppression of energy intake." (PMID 39785828, 2025). "Furthermore, mice with a high-fat diet or genetically induced obesity were characterized by an increased level of CCK in the lungs and the administration of the CCK-1 antagonists suppressed the innate airway hyperresponsiveness to methacholine in obese animals." (PMID 38542187, 2024). "Therefore, we hypothesized that physiologic β cell-derived CCK could be a local driver of tumorigenesis in obesity via endocrine (islet)–exocrine (acinar cell) signaling." (PMID 37648285, 2023).
Obesity (continued). "Tissue-specific conditional CCK or CCKAR knockout in obese mice may be needed to completely rule out the possible role of CCK/CCKAR in the brainstem in modulating obesity-associated AHR." (PMID 36599824, 2023). "Possible explanations about the relationship of MedDiet and overweight and obesity for children are, the MedDiet is rich in dietary fiber, which may protect against weight gain by increasing satiety through prolonging chewing and releasing the cholecystokinin." (PMID 37046233, 2023). "Therefore, it is important to consider the mechanisms by which a high fat diet attenuates leptin signaling as described in prior sections as it may have a significant role in the blunted CCK activity commonly seen in HFD-induced obesity." (PMID 37571301, 2023). "It has previously been suggested that pure allosteric modulators may be advantageous as CCK1R-active drugs to be used in obesity - a positive allosteric modulator of CCK1R possessing no intrinsic agonist activity could enhance the satiety effect of natural CCK when it is released after a meal." (PMID 34149622, 2021). "Therefore, we tested the hypothesis that heightened eCB signaling at CB1Rs in the small-intestinal epithelium in our mouse model of western diet-induced obesity drives overeating by blocking nutrient-induced release of CCK-8." (PMID 33916974, 2021). "Future studies need to measure leptin in conjunction with the other appetite-regulating peptides (acylated ghrelin, PYY, GLP-1, CCK and PP) to enable a better understanding of how exercise-induced responses to appetite-regulating hormones might differ in obesity." (PMID 32729763, 2020). "Interestingly, our finding that AgRP neurons become resistant to both ghrelin and CCK, along with substantial prior evidence of leptin resistance in obesity, suggests that AgRP neurons may become generally resistant to hormonal input following weight gain." (PMID 32720646, 2020). "We reported that hyperphagia and increased meal size associated with WD-induced obesity in mice are dependent on (i) elevated levels of endocannabinoids in the upper small-intestinal epithelium and (ii) CB1R-mediated inhibition of nutrient-induced signaling of the satiation peptide, cholecystokinin." (PMID 32962222, 2020). "Furthermore, we speculate that manipulating this pathway could have important therapeutic implications in the treatment of diseases such as diabetes, obesity or anxiety given the biologic effects of CCK in the intestine and central nervous system." (PMID 31811178, 2019). "The release of endogenous CCK and GLP-1 suggests, paradoxically, that fat could exert strong effects on the development of satiation and the strength of post-meal satiety, despite an association between high fat over-consumption and obesity." (PMID 18307772, 2008). "Intraduodenal calcium enhances the effect of intraduodenal Trp to stimulate CCK, GLP-1, and PYY and suppress energy intake in males with obesity." (PMID 39785828, 2025). "Consistent with our observations in individuals of normal weight, calcium enhanced the effects of Trp to stimulate plasma CCK, GLP-1, and PYY, in a dose-dependent manner, in males with obesity." (PMID 39785828, 2025). "Disturbances in this regulation in relation to cholecystokinin (CCK) and glucagon-like peptide-1 (GLP-1), hormones that regulate appetite and food intake, promote weight loss, and improve hyperglycemia, may be important in the context of the pathomechanism of obesity." (PMID 40141148, 2025). "In obesity and T2D, often there are blunted PYY, higher ghrelin, and, possibly, lower cholecystokinin (CCK) responses—all tilting the energy balance toward weight gain." (PMID 40871736, 2025). "Combining CCK with other hormones such as GLP-1, amylin, or leptin shows promise for synergistic effects in treating obesity and T2DM, highlighting the therapeutic potential of CCK-based strategies." (PMID 41150735, 2025).
Obesity (continued). "This randomized, double-blind clinical trial showed that daily supplementation of the synbiotics MN-Gup-GOS-XOS for 12 weeks reduced body fat percentage, waist, serum LDL-C, and increased PYY, CCK, OXM, GSH in individuals with obesity." (PMID 39664910, 2024). "Further, in diet-induced obesity, it has been shown that small intestinal signaling via the CB1R pathway inhibits nutrient-mediated CCK release via gut–brain dependent mechanisms." (PMID 38613104, 2024). "Lipid-lowering treatment has the potential to alleviate obesity-induced airway hyperresponsiveness and lung fibrosis by inhibiting the NLRP3 inflammasome, RAS and cholecystokinin activity." (PMID 38762465, 2024). "In this study, supplementation of MN-Gup-GOS-XOS increased the levels of PYY, CCK, and OXM in individuals with obesity, which provided a possible explanation for the mechanism of MN-Gup-GOS-XOS reducing LDL-C." (PMID 39664910, 2024). "In summary, our data indicate that in the HFD-induced obesity model, there are heightened activation of RAS and NLRP3 inflammasome signaling, alongside increased CCK activity." (PMID 38762465, 2024). "Synbiotics supplementation significantly decreased body fat percentage, waist, and serum low-density lipoprotein cholesterol (LDL-C), increased peptide YY, cholecystokinin, oxyntomodulin, GSH (glutathione peroxidase) in individuals with obesity." (PMID 39664910, 2024). "In diet-induced obesity, the increase in CB1 receptor activity inhibits CCK-8, resulting in delayed satiation and overeating." (PMID 38002684, 2023). "However, the requirement for β cell CCK in obesity-driven PDAC has not yet been firmly established in preclinical models and competitive CCK receptor antagonists may not be potent enough to counter the presumably high local concentrations of obesity-induced CCK within the pancreas." (PMID 37648285, 2023). "Previous studies have suggested the implication of obesity with the reduced post-prandial response of glucagon-like peptide-1 (GLP-1), cholecystokinin (CCK), and peptide YY (PYY), as well as the unleashed post-prandial reaction of ghrelin." (PMID 36834794, 2023). "The co-administration of CCK with GLP-1 and leptin substantially enhances metabolic benefits under conditions of obesity and diabetes." (PMID 35334929, 2022). "Altogether we showed in a second group, a specific reduction of CCK and GLP-1 cell lineages in obesity and T2D." (PMID 33037328, 2021). "Since high-fat diet feeding attenuates CCK-induced activation of vagal afferents as well as responses in downstream brain regions, alterations in GLP1R vagal afferent control of meal-related glycemia may also provide a neural mechanism underlying impaired glycemic control in obesity." (PMID 34043943, 2021). "Since CCK has two known receptors, CCKAR and CCKBR20, we then tested if a specific receptor signaling pathway is more relevant in the islet or changed by obesity." (PMID 32071395, 2020). "Possibly, in a longer experimental time, the CCK secretagogue isolated or purified from tamarind seeds could present better results regarding appetite control and, consequently, weight loss, considering that TTI decreased food consumption in animals with obesity." (PMID 29322840, 2018). "Interestingly, this normal switching between feeding and fasting states is blunted in diet-induced obesity rats as demonstrated by a loss of vagal sensitivity to leptin, which is known to act synergistically with CCK on VAN to potentiate the satiety effect of CCK." (PMID 28443064, 2017). "In SP1 mice, a decrease in the efficacy of CCK to reduce meal size and c-Fos expression in hind brains at least partly contributed to SP1-induced hyperphagia and obesity." (PMID 26569394, 2015). "It is, accordingly, important to determine whether the effects of calcium and Trp to stimulate CCK, GLP-1, and PYY secretion and pyloric pressures and suppress energy intake are maintained in individuals with obesity." (PMID 39785828, 2025).